CFTR (CF transmembrane conductance regulator)
Diseases named in the same sentence as CFTR in open-access papers (continued):
Sharing a sentence is not in itself a finding about the gene and the disease.
bacterial infection (continued). "Since bacterial infections are one of the hallmarks of CF lung disease, the effects (if any) of CFTR modulators on bacteria could impact their efficacy." (PMID 36625583, 2023). "These CFTR polymorphisms associated with COPD may facilitate the acquired dysfunction of CFTR, especially upon sustained exposure to environmental pathogens, such as CS and bacterial infection." (PMID 36768629, 2023). "Decreased or absent functional CFTR protein in airway epithelial cells leads to abnormally viscous mucus and impaired mucociliary transport, resulting in bacterial infections and inflammation causing progressive lung damage." (PMID 30800069, 2019). "Our results corroborate with other studies performed in various epithelial and non-epithelial cells indicating that deletion or mutations of CFTR confer a propensity to exaggerated inflammatory responses that are not related to bacterial infection." (PMID 27588407, 2016). "Mutations in the cftr gene lead to the synthesis of a non-functional CFTR, causing dehydration of the airway surface liquid, thereby impeding mucociliary clearance and creating a favorable microenvironment for bacterial infections." (PMID 23505426, 2013). "CFTR malfunction results in airway surface dehydration and impaired mucociliary clearance leading to airway mucus obstruction, neutrophilic inflammation and bacterial infection." (PMID 23991177, 2013). "The ΔF508 mutation in CFTR prevents the localisation of CFTR into the microdomains and bacterial infection is not cleared." (PMID 21490807, 2011). "Therefore, CFTR-targeted therapies, by restoring CFTR function and reducing lung tissue redox status, might confer a better control of bacterial infection." (PMID 37619220, 2023). "However, even with CFTR modulator therapy, bacterial infections persist." (PMID 37998353, 2023). "In CF patients, the lack of CFTR chloride channel activity leads to progressive pulmonary obstruction associated with critical and constant neutrophil-dominated endobronchial inflammation and overwhelming bacterial infection." (PMID 32848733, 2020). "In a previous study, we demonstrated for the first time that mutant CFTR directly drives EMT, independently of secondary effects such as chronic inflammation or bacterial infection." (PMID 40910003, 2025). "In the era of CFTR modulators, ETI administration can improve clinical outcomes, reducing both (myco)bacterial infections and pulmonary exacerbations in PWCF." (PMID 40249250, 2025). "We previously demonstrated that mutant CFTR directly drives partial EMT, independently of secondary events such as bacterial infection or inflammation." (PMID 40910003, 2025). "NEW & NOTEWORTHY Gene expression responses by CF AECs exposed to ETI suggest that in addition to improving CFTR channel function, ETI is likely to enhance resistance to bacterial infection by increasing levels of beta-defensin 1 (hBD-1)." (PMID 39437760, 2024). "After the bacterial infection of HBE, epithelial cultures were processed for CFTR mRNA quantitation by qRT-PCR." (PMID 37998353, 2023). "Although these data support the hypothesis that the abnormal macrophage activity, due to the lack of CFTR might be one of the causes of persistent bacterial infections and exuberant inflammatory responses in CF, at present the contribution of CFTR in the physiology of human macrophages is unknown." (PMID 21625641, 2011). "It has been reported that under the circumstances of inflammation, or upon bacterial infection, the increased release of inflammatory cytokines such as IL-1β and TNF-α have potent effect on up-regulation of CFTR in epithelial cells." (PMID 21151921, 2010). "Taken together, the present finding has revealed a previously undefined role of CFTR and its mediated prostatic HCO3− secretion in the host defense against bacterial infection." (PMID 21151921, 2010).
bacterial infection (continued). "In the absence of bacterial infection, the restoration of chloride ion secretion through the expression of a normal CFTR gene significantly improved the inflammatory profile of CFBE-dF cells." (PMID 41487515, 2025). "In the absence of CFTR activity, abundant mucus accumulation, bacterial infection and inflammation characterize CF airways, in which inflammation-associated tissue remodeling and damage gradually destroys the lung." (PMID 38699141, 2024). "CFTR modulators are highly effective and reduce the need for intravenous antibiotics; however, they are not suitable for all patients and do not clear bacterial infection, so do not completely suppress the need for intravenous antibiotics." (PMID 39108933, 2024). "Collectively, these findings point toward a scenario that defective CFTR leads to exaggerated NF-κB-mediated pro-inflammatory responses that are not related to bacterial infection." (PMID 27588407, 2016). "Despite the intriguing evidence on the pathogenic role of smoke exposure in increasing the risk of bacterial infection, the underlying mechanism(s) by which SHS exposure impairs CFTR dependent bacterial phagocytosis in macrophages is not fully understood." (PMID 25794013, 2015). "Our results implicate a critical CFTR-dependent barrier function that is defective during RSV infection in CF airway cells, potentially contributing to more severe pulmonary manifestations, including secondary bacterial infection and persistence in CF lungs." (PMID 24056672, 2013). "The present study has investigated the possible mechanism underlying this pH change and demonstrated for the first time the involvement of CFTR in mediating prostatic HCO3− secretion, which may be enhanced upon bacterial infection or inflammation." (PMID 21151921, 2010). "The observed upregulation of CFTR and CAII upon bacterial infection or LPS challenge could be due to the elevated levels of cytokines induced by the pathogens." (PMID 21151921, 2010). "Together with the demonstrated CFTR and CAII upregulation, therefore enhanced prostatic HCO3− secretion, upon bacterial infection, the present finding suggests a host defense mechanism against bacterial infection in the prostate." (PMID 21151921, 2010). "Thus, we aimed to establish whether and how bacterial adaptation affects the antimicrobial activity of CFTR modulators, including ELX and ETI, and the impact of bacterial infection on PK." (PMID 36625583, 2023). "There is controversy over whether exaggerated IL-8 production is an intrinsic property of airway epithelial cells lacking normal CFTR or whether it is the result of impaired mucociliary clearance and bacterial infection." (PMID 23977375, 2013).
autosomal recessive disease (32 papers, 2005 to 2025). Autosomal recessive form of disease. "CF is one of the most common autosomal recessive diseases among Caucasians and is caused by mutations in the CFTR gene." (PMID 40128832, 2025). "CF is a life-threatening autosomal recessive inherited disease caused by mutations in the gene encoding the CF transmembrane conductance regulator (CFTR) protein, a chloride and bicarbonate channel residing at the apical membrane of the secretory epithelia." (PMID 40868613, 2025). "CF is an autosomal recessive disease due to mutations in the CF Transmembrane Conductance Regulator (CFTR) gene, which in Caucasian populations has an incidence between 1/3000 and 1/6000, corresponding to carrier rates of 1/28 and 1/40, respectively." (PMID 38339210, 2024). "CF is a multisystemic autosomal recessive disease caused by a mutation in the CF transmembrane conductance regulator (CFTR) gene, severely damaging the respiratory and digestive systems." (PMID 37256139, 2023). "CF is a multisystemic autosomal recessive disease with an incidence of 1/3,000–10,000 newborns, which is caused by a wide variety of mutations in the CF transmembrane conductance regulator (CFTR) gene." (PMID 36568297, 2022). "It is a monogenetic autosomal recessive disease caused by loss-of-function mutations in the gene encoding the chloride channel cystic fibrosis transmembrane conductance regulator (CFTR), the impairment of which leads to ionic disequilibria in exocrine organs." (PMID 33348555, 2020). "CF is one of the most common life-threatening autosomal recessive diseases in Caucasians, among which clinical features and the CFTR mutation spectrum are well defined." (PMID 30558651, 2018). "CF is a life-shortening autosomal recessive inherited disease caused by the absence or dysfunction of CFTR channel activity, resulting from mutations in the CFTR gene." (PMID 28869532, 2017).
respiratory disease (27 papers, 2010 to 2026). "Respiratory disease remains the leading cause of death in patients with CF (PwCF) despite CFTR function improvement by the CFTR modulators developed in the last decade." (PMID 36911035, 2023). "Respiratory disease in pwCF is mainly caused by CFTR dysfunction in airway epithelial cells, which disturbs airway surface fluid secretion and causes the accumulation of thick mucus in the airways." (PMID 36293514, 2022). "Respiratory disease in CFTR carriers is associated with older age and may cause significant morbidity." (PMID 35668512, 2022). "The absence of toxicity and the pleiomorphic effect of c407 suggest that this compound might be clinically relevant and implementable not only for CF but also for other respiratory diseases associated with the loss of function of misfolded CFTR." (PMID 35413967, 2022). "The effect of CFTR modulator therapy on specific fungal and other rarer microbes is still unknown, and this is also true regarding the long-term impact of these therapies on specific virus-associated respiratory disease, although the initial signals are largely positive." (PMID 36835487, 2023). "This defect impairs CFTR-dependent anion conductance in airway epithelia, which leads to a severe respiratory disease." (PMID 35922154, 2022). "Nevertheless, based on the origin of CF respiratory disease, it remains postulated that airway epithelial models are more predictive for determining CFTR modulator responses." (PMID 35922154, 2022). "Given that CFTR modulators are of interest in other respiratory diseases such as Chronic Obstructive Pulmonary Disease45–47, this may impact understanding of modulator effects outside of CF specifically." (PMID 37491532, 2023). "This dual corrector and anti-inflammatory activity is thus interesting in the context of the CF respiratory disease that is triggered by a defective muco-ciliary clearance due to a decreased CFTR dependent chloride (Cl−) transport but also an overactive inflammatory response." (PMID 35413967, 2022). "Altogether, this dual CFTR correction and anti-inflammatory activity might be interesting in the context of respiratory diseases which combine defects in CFTR and increased NF-kB mediated inflammation." (PMID 35413967, 2022). "As CFTR-autophagy becomes impaired in both CF and COPD, cells have chronically elevated intracellular levels of ROS altering cellular homeostasis, causing exacerbations and accelerating the pathogenesis and progression of these respiratory diseases." (PMID 32847034, 2020). "Importantly, none of the CFTR mutations correlate with sweat chloride levels and only few of the more than 1,500 identified mutations in CFTR result in an expected respiratory disease phenotype in homozygous or compound heterozygous patients." (PMID 20420703, 2010). "Our study suggests that cAMP and CFTR modulation has potential as a therapeutic strategy for elevating ASL pH and may be beneficial for respiratory diseases with ASL abnormalities." (PMID 41635008, 2026).
inflammation (17 papers, 2013 to 2025). Aberrant reaction of the microcirculation characterized by movement of fluid and leukocytes from the blood into extravascular tissues. "In a SphK2 knockout (SphK2−/−) mouse model, we revealed that CS-induced pulmonary inflammation and fibrosis were significantly decreased, and SphK2 deficiency rescued CFTR activity and preserved pulmonary function by suppressing the S1P secretion." (PMID 36226596, 2023). "Together, these results are suggestive of CFTR as a therapeutic target in HF-associated lung inflammation." (PMID 35055052, 2022). "In summary, platelets and neutrophils are key players during LPS or bacteria-induced lung inflammation in CFTR-deficient mice." (PMID 24671173, 2014). "However, administration of S1P1 agonist in SphK2−/− mice markedly suppressed CFTR expression, abolished the protective effect of SphK2 deficiency on small airways remodeling and pulmonary inflammation after CS exposure." (PMID 36226596, 2023). "Taken together, lipoxin A4 and PAF are involved in E. coli or LPS-induced lung inflammation in CFTR-deficient mice, suggesting that lipoxin A4 and PAF might be therapeutic targets for ameliorating CFTR-deficiency deteriorated lung inflammation." (PMID 24671173, 2014). "During lung inflammation, dysfunction of CFTR promotes neutrophil-platelet interaction, by which synthesis of lipoxin A4 initiates." (PMID 24671173, 2014). "In contrast, the absence of CFTR appeared to modify cellular uptake of NP and caused a moderate impairment of the resolution of a by particle instillation induced neutrophilic airway inflammation." (PMID 24758489, 2014).
metabolic disease (10 papers, 2015 to 2025). A congenital disorder (due to inherited enzyme abnormality) or acquired (due to failure of a metabolically important organ) disorder resulting from an abnormal metabolic process. "Finally, after considering broad differential diagnosis, introducing treatment specific for CF and excluding other metabolic diseases, a third expanded genetic test revealed the presence of a rare pathogenic mutation in both alleles of the CFTR gene: c.4035_4038dupCCTA (p.Ser1347ProfsX13)." (PMID 32103733, 2020). "It is unclear whether Trikafta and other highly effective CFTR modulator therapies will reverse intestinal and metabolic disease in people with CF." (PMID 39002195, 2024). "One of the LP variants, CFTR: rs140455771, was the only variant identified in SIDS030 and SIDS072 after a thorough review of genes associated with cardiovascular/metabolic diseases and CoQ deficiency, suggesting that this variant might be a finding that deserves further functional investigation." (PMID 38844616, 2024). "In addition, the 4 VUS identified in this study (CFTR: rs1800120, TBC1D24: rs754558646, HTT: rs779780620, and FDX2: rs897162037) were found to coexist with several other P/LP variants or VUS in genes associated with cardiovascular/metabolic diseases or CoQ deficiency." (PMID 38844616, 2024). "Despite several reports relating GRK5 expression levels with neurodegenerative, cardiovascular, and metabolic diseases, we have not found significant alterations in GRK5 mRNA when comparing cells expressing wt- or p.Phe508del-CFTR or across DMSO versus 9g or ETI." (PMID 40040803, 2025).
immune dysfunction (9 papers, 2014 to 2025). "Taken together, these results support the notion that CFTR mutations lead to immune dysfunction and deficiency." (PMID 35315363, 2022). "The characterization of etiologic defects in autophagy associated with CFTR mutations has greatly advanced our understanding of immune dysfunction in CF." (PMID 24434788, 2014). "However, there is a continued scientific question examining the role of CFTR-induced immune dysfunction versus immune dysregulation secondary to chronic infection and perpetual inflammation." (PMID 40429486, 2025). "Immune dysregulation may be an important contributor to the pathobiology of CF where chronic airway infection may augment the effects of CFTR-mediated immune dysfunction." (PMID 31262295, 2019).
intestinal disease (7 papers, 2015 to 2026). "Studies demonstrated that genes other than CFTR relate to intestinal disease in humans and CF-mouse." (PMID 29915289, 2018). "We obtained C57BL/6J mice with and without the human G542X mutations to the CFTR gene to act as models of whole-body CFTR knockout and related intestinal disease." (PMID 39002195, 2024).
infectious disease (6 papers, 2019 to 2024). A disorder directly resulting from the presence and activity of a microbial, viral, or parasitic agent in humans. "CFTR mutations may also provide resistance to infectious disease by reducing the amount of sulfate available to Mycobacterium tuberculosis and cause lower rates of tuberculosis infection." (PMID 38952711, 2024). "A final application of miRNA-mediated downregulation of CFTR is in the field of infectious diseases." (PMID 37104011, 2023). "The second example of possible applications of CFTR downregulation in infectious diseases is related to the role of CFTR in the life cycle of SARS-CoV-2, responsible for the COVID-19 pandemic." (PMID 37104011, 2023). "Syntaxin-17 (STX17), a SNARE protein, interacts with CFTR and the loss of the CFTR-STX17 interaction impairs bacterial clearance and could play a critical role in infectious diseases among CF patients." (PMID 35269585, 2022).
kidney disease (6 papers, 2017 to 2025). "This, along with enhanced epithelial-to-mesenchymal and fibrosis seen in CFTR mutant mice, may underlie the frequent kidney disease observed in CF." (PMID 40807208, 2025). "As the urine is sterile, the study of exosomes present in this biofluid undoubtedly provides information for CFTR-related renal disease and possibly CF physiopathology." (PMID 32927759, 2020). "Of note, despite the abundant expression of CFTR in mammalian kidney, the role of CFTR in kidney disease development is unclear." (PMID 28701694, 2017). "The Cl−-transporting proteins CFTR, SLC26A9, and anoctamin (ANO1; ANO6) appear to have more in common than initially suspected, as they all participate in the pathogenic process and clinical outcomes of airway and renal diseases." (PMID 37686084, 2023).
cardiovascular disease (4 papers, 2018 to 2025). "Therefore, additional studies are warranted in order to define the contribution of Nrf2 to intestinal lipoprotein metabolism and cardiovascular diseases, especially in response to CFTR deficiency that affects the expression of Nrf2." (PMID 29954133, 2018). "CFTR might serve as a novel target for endothelial protection in cardiovascular diseases characterized by elevation of FFAs." (PMID 33123317, 2020).
heart disease (3 papers, 2016 to 2025). "For example, weight gain as a result of CFTR modulator therapy has been linked to associated comorbidities that affect the general population, like increased heart disease." (PMID 40202901, 2025).
adenocarcinoma (2 papers, 2021 to 2022). A common cancer characterized by the presence of malignant glandular cells. "Gelsolin (GSN), an actin severing protein, is described as important for CFTR activation but it is also regulated by β-catenin to promote adenocarcinoma cell migration." (PMID 35500936, 2022).
congenital disorders of metabolism (2 papers, 2022 to 2025). "For instance, mutations in the Cystic Fibrosis Transmembrane Conductance Regulator (CFTR) primarily cause congenital disorders of metabolism (CDM), with minimal impact on other diseases." (PMID 40665056, 2025).
neurodegenerative disease (2 papers, 2012 to 2021). A disorder of the central nervous system characterized by gradual and progressive loss of neural tissue and neurologic function. "Initially implicated in the pathogenesis of CFTR and HIV-1 transcription, nuclear factor TDP-43 was subsequently found to be involved in the origin and development of several neurodegenerative diseases." (PMID 22577517, 2012).
digestive system cancer (1 paper, 2025). A primary or metastatic malignant neoplasm involving any part of the digestive system. "Indeed, we found digestive system cancers were 2.7 times higher in CFTR carriers than controls, echoing a finding reported in a UK biobank study of older CFTR carriers—although not significant in the 44 cases analyzed here." (PMID 40468859, 2025).